SPMIP7 (sperm microtubule inner protein 7)
Description:
Essential for normal spermatogenesis.
Synonyms: C7orf72; SPATA48
Tractability: No criterion of Open Targets' tractability assessment is met for any kind of drug.
Gene: Protein-coding gene on chromosome 7 (50,095,883 to 50,159,256, forward strand). Ensembl gene ENSG00000164500.
Subcellular location (Human Protein Atlas): Connecting piece; Mid piece; Principal piece
Gene Ontology:
Biological process: spermatogenesis
Genetic constraint (gnomAD): Loss-of-function variants: 19 observed, 20.59 expected, observed/expected ratio (o/e) 0.92, 90% interval 0.64 to 1.35. The upper end of that interval is the gene's LOEUF score, 1.35, which puts it in group 5 of 6, group 1 being the genes least tolerant of losing a copy. Missense variants: 342 observed, 369.8 expected, observed/expected ratio (o/e) 0.92, 90% interval 0.85 to 1.01. Synonymous variants: 107 observed, 129.07 expected, observed/expected ratio (o/e) 0.83, 90% interval 0.71 to 0.97.
Homologues: Orthologues: chimpanzee SPMIP7 (99% identical), macaque SPMIP7 (97% identical), rabbit SPMIP7 (83% identical), pig SPMIP7 (79% identical), dog SPMIP7 (79% identical), mouse Spmip7 (75% identical), rat Spmip7 (75% identical), zebrafish SPMIP7 (32% identical).
Diseases named in the same sentence as SPMIP7 in open-access papers:
SPMIP7 is named in the same sentence as 4 diseases in open-access papers, as found by Europe PMC text mining. Sharing a sentence is not in itself a finding about the gene and the disease. The quoted sentences say what the papers report.
male infertility (1 paper, 2026). The inability of the male to effect fertilization of an ovum after a specified period of unprotected intercourse. "Importantly, SPMIP7 is believed to be linked to male infertility and a target for novel male contraceptives." (PMID 41550493, 2026).
SPMIP7 also shares sentences with these, for which no sentence is quoted: Crohn disease (1 paper); glioma (1); inflammatory bowel disease (1).